STAT3 (signal transducer and activator of transcription 3)
Diseases named in the same sentence as STAT3 in open-access papers (continued):
Sharing a sentence is not in itself a finding about the gene and the disease.
clear cell renal cell carcinoma (26 papers, 2014 to 2026). "Recent research also has identified ApoC1 which promotes renal clear cell carcinoma metastasis through activation of the STAT3 pathway and is a potential novel diagnostic and prognostic marker for clear cell renal carcinoma." (PMID 36891052, 2023). "Exosomes AP000439.2 originated from clear cell renal cell carcinoma, directly interact with STAT3 protein and p-STAT3 in macrophages, and activate the NF-κB signaling pathway to facilitate M2 polarization of macrophages." (PMID 40612677, 2025). "For example, constitutive activation of JAK2/STAT3 signaling has been reported to contribute to tumor growth and metastasis in clear cell renal cell carcinoma, gallbladder cancer, and other malignancies, highlighting its role as a potential therapeutic target." (PMID 40586636, 2025). "(2022) demonstrated that IL-1RII can also promote oncogenic signaling by activating the Janus kinase 2 (JAK2)/signal transducer and activator of transcription 3 (STAT3) pathway in clear cell renal cell carcinoma (ccRCC)." (PMID 41211420, 2025). "Aberrant activation of STAT3 has been related to development of nearly 50% of human cancers including clear cell renal cell carcinoma (ccRCC)." (PMID 37945711, 2023). "For example, APOC1 facilitates clear cell renal cell carcinoma metastasis by STAT3 pathway activation." (PMID 34298684, 2021). "Using the results of EC classification, we also quantified proliferation (Ki67) and activity in important signal transduction pathways (MAP kinase, STAT3) in immunostained human clear cell renal cell carcinoma and other tumors." (PMID 24603893, 2014). "Similarly, the cycle regulator CyclinD1 was maintained as a target gene of the JAK2/STAT3 signaling pathway subjected to the regulation of PBX1 in clear cell renal carcinoma." (PMID 36361531, 2022). "In clear cell renal cell carcinoma, AP000439.2, also delivered via exosomes, directly binds to STAT3 and activates the STAT3/NF‐κB pathway." (PMID 39247621, 2024). "It has been reported that ILF3/ERp57 forms a positive feedback loop mediating STAT3; therefore, ILF3/STAT3/ERp57 together promote clear cell renal cell carcinoma proliferation." (PMID 38136312, 2023). "In clear cell renal carcinoma, APOC1 facilitates the activation of signal transducer and activator of transcription (STAT3) and promotes the metastasis of tumor cells." (PMID 37576389, 2023). "In contrast to normal tissues, STAT3-dependent EGFR and PAR-1 activation in endothelial cells OF clear cell renal cell carcinoma was significantly increased." (PMID 29291033, 2017). "In contrast to normal tissue, STAT3-dependent transactivation of EGFR and PAR-1 in endothelial cells of clear cell renal cell carcinoma was significantly increased." (PMID 29291033, 2017). "Taken together, our findings suggest that the IL6/STAT3 pathway plays a crucial role in the normal fibroblast-enhanced clear-cell renal cell carcinoma metastasis, while GATA3 may mitigate this effect by inhibiting IL6/STAT3 signaling." (PMID 31636361, 2020). "In addition, higher expression of FABP7 was seen in clear cell renal cell carcinoma and the authors suggested that the gene activates the ERK and STAT3 signalling pathways." (PMID 30845926, 2019).
endothelial dysfunction (26 papers, 2010 to 2026). In vascular diseases, endothelial dysfunction is a systemic pathological state of the endothelium (the inner lining of blood vessels) and can be broadly defined as an imbalance between vasodilating and vasoconstricting substances produced by (or acting on) the endothelium. "Collectively, this data suggests that STAT3-mediated programming is associated with endothelial dysfunction following exposure to CAR T-cell secretion." (PMID 37914765, 2023). "The sub-lethal inhibition of STAT3 caused endothelial dysfunction, demonstrated by reduced nitric oxide release in response to acetylcholine and reduced barrier function of the endothelial monolayer." (PMID 36293020, 2022). "We demonstrate that sub-lethal inhibition of STAT3 is sufficient to cause endothelial dysfunction, and that endothelial specific attenuation of STAT3 leads to increased infarct following MCAO." (PMID 36293020, 2022). "Thus, decreased serum-induced endothelial STAT3(Y705) activation may play an important role in PE-associated endothelial dysfunction and reduced endothelial STAT3(Y705) phosphorylation and may increase post-preeclamptic CVD risk after delivery." (PMID 39918020, 2025). "Signal transducer and activator of transcription 3 (STAT3), a latent cytoplasmic transcription factor involved in endothelial cell differentiation, survival, and angiogenesis, may play an important role in preeclampsia-associated endothelial dysfunction." (PMID 36686428, 2022). "Regardless of the inconsistent expression of LIF, it has been shown that LIF increases adhesion molecules via the JAK/STAT3 pathway, inducing inflammation and leading to endothelial dysfunction." (PMID 41006365, 2025). "In humans, STAT3 pathway signaling directly relates to the expression of inflammatory mediators, which act in leukocyte activation and the progression of endothelial dysfunction." (PMID 39274184, 2024). "Collectively, this data suggests that the observed endothelial dysfunction following CAR T-cell treatment is at least partially regulated through STAT3 programming." (PMID 37914765, 2023). "STAT3 plays an important part in normal endothelial cell biology, and endothelial dysfunction is known to contribute to initiation of transplant-related inflammatory complications." (PMID 33523338, 2021). "Although previous studies suggested that resistin caused endothelial dysfunction via activated SOCS3 and JAK/STAT3 pathway, the upstream mechanisms underlying resistin’s action are not fully clear." (PMID 24526524, 2014). "H2S ameliorates endothelial dysfunction through the anti-inflammatory effect of the PPARδ/SGLT2/p-STAT3 signaling pathway in senescent ECs and may be a potential therapeutic target for anti-ageing treatment." (PMID 37587757, 2023). "Janus kinase type 2 (JAK2) and signal transducer and activator of transcription 3 (STAT3) have been reported to participate in processes directly related to pulmonary artery remodeling such as smooth muscle proliferation, endothelial dysfunction, and inflammation." (PMID 34067108, 2021). "STAT3 activation has been shown to have a number of effects, including inhibition of eNOS promoter activity and reductions in eNOS gene expression, thereby providing a mechanistic link by which IL-6 serves to produce endothelial dysfunction." (PMID 25400581, 2014). "Mechanistically, IL-6 promotes endothelial dysfunction, smooth-muscle proliferation, and thrombogenic remodeling through JAK/STAT3 signaling, all of which contribute to plaque instability and restenosis after CEA." (PMID 41440557, 2025).
endothelial dysfunction (continued). "Astragaloside IV activates the JAK2/STAT3 and ERK1/2 signaling pathways, upregulates the expression of endothelial eNOS and the production of NO, and improves endothelial dysfunction." (PMID 34840664, 2021). "This endothelial dysfunction may contribute to the pathogenesis of surrounding brain tissue following MCAO, a phenomenon exacerbated in our mouse model of attenuated endothelial STAT3." (PMID 36293020, 2022).
keloid (26 papers, 2013 to 2025). An irregularly shaped, elevated mark on the skin caused by deposits of excessive amounts of collagen during wound healing. "We next compared fibroblasts from patients with loss-of-function mutations in STAT3 to contrast against the keloid cell line with hyper-activity of STAT3." (PMID 33662027, 2021). "Overall, our findings reproduce the claims of many prior reports, suggest a potential role of folate metabolism in keloid pathogenesis, and present some of the first insights into the metabolic consequences of monogenic loss of STAT3 activity." (PMID 33662027, 2021). "IL-17 induces autophagy dysfunction to promote inflammatory cell death and fibrosis in keloid fibroblasts via the STAT3 and Hypoxia Inducible Factor-1α (HIF-1α) dependent signaling pathways." (PMID 39799030, 2025). "EGCG’s potent inhibition of STAT3 activation, confirmed by inhibitor and siRNA studies, further decreases collagen expression, highlighting its therapeutic potential for controlling keloid development." (PMID 41424791, 2025). "IL-17 induced stromal cell-derived factor-1 and profibrotic factor in keloid-derived skin fibroblasts via the signal transducer and activator of transcription-3 (STAT3) pathway." (PMID 39799030, 2025). "The inhibition of STAT3 expression to block IL-6’s signaling pathway or inhibit IL-6 in keloid fibroblast cultures has resulted in keloid tissue fibroblasts losing collagen production, impairing their proliferation." (PMID 39091289, 2024). "We proceeded to investigate the potential involvement of the STAT3 signaling pathway in the inhibitory effect of DMC-HA on keloid fibroblasts." (PMID 38284901, 2024). "This suggests that DMC-HA has the potential to inhibit keloid formation by mitigating STAT3 phosphorylation." (PMID 38284901, 2024). "Previous studies have demonstrated that IL-6 stimulates the phosphorylation of pY705 STAT3 in keloid fibroblasts to a significantly higher degree than in normal fibroblasts." (PMID 38284901, 2024). "In our study, p-STAT3 expression significantly increased in keloid fibroblasts following exogenous IL-6 stimulation, but this elevated p-STAT3 was significantly suppressed by DMC-HA intervention." (PMID 38284901, 2024). "IL-6 and IL-17, in particular, have been shown to elicit STAT3 phosphorylation in both healthy and keloid fibroblasts." (PMID 39201463, 2024). "This activation suggests that STAT3 plays a crucial role in keloid pathogenesis, potentially driving the excessive collagen production and proliferation characteristic of keloids." (PMID 39201463, 2024). "Subsequent addition of DMC-HA resulted in a reduction in p-STAT3 levels induced by exogenous IL-6 in keloid fibroblasts, as evidenced by Western blot analysis (P<0.05)." (PMID 38284901, 2024). "Through upregulation of hypoxia-inducible factor-1α (HIF-1α) and STAT3, IL-17 impairs autophagy of both normal and keloid fibroblasts, resulting in increased necroptosis and fibrosis." (PMID 37033989, 2023). "Recently, RNA sequencing analyses confirmed robust expression of JAK3 in keloid tissue, and positioned STAT3 in a feedforward loop regulating a myriad of downstream target genes involved in keloidogenesis." (PMID 37033989, 2023). "ASC-J9, an inhibitor of STAT3 phosphorylation, has shown efficacy in suppressing keloid fibroblasts." (PMID 37033989, 2023). "Epigallocatechin-3-gallate (EGCG), a green tea extract, has been found to possess chemopreventive properties, including suppression of STAT3 signaling, potentially inhibiting keloid growth." (PMID 37033989, 2023). "IL-17-mediated enhancement of stromal cell-derived factor-1 (SDF-1) in keloid fibroblasts further reinforces Th17 differentiation via STAT3 mediation." (PMID 37033989, 2023). "Signal transducer and activator of transcription 3 (STAT3) has been found to mediate the biological functions of keloid fibroblasts (KFs)." (PMID 35628356, 2022).
keloid (continued). "STAT3 expression and phosphorylation are increased in keloids, whereas the knockdown of STAT3 in KFs reduces their capacities of collagen synthesis, proliferation, and migration." (PMID 35628356, 2022). "Previous studies found that pSTAT3 and STAT3 are overexpressed in keloid fibroblasts and that STAT3 interference by siRNA, Cucurbitacin I, and AG490 inhibits cell proliferation, migration, and ECM production in KFs." (PMID 35628356, 2022). "The expression of IL-17, HIF-1α and STAT3 was significantly increased in keloid tissue, and autophagosome-to autophagolysosome conversion was defective in KF." (PMID 35757697, 2022). "The expression of HIF-1α and STAT3 was significantly increased in the transitional region where skin tissue changes into keloid tissue." (PMID 35757697, 2022). "In the same context, it was demonstrated that STAT3 phosphorylation inhibition reduces the production of collagen in keloid scars." (PMID 34490235, 2021). "Our work expands on the current literature to directly link JAK1/2, STAT3, and HIF1α to keloid pathology, folic acid responses, and Warburg physiology; however, other signaling pathways beyond these identified pathways are likely involved for each finding." (PMID 33662027, 2021). "NTP can therefore have beneficial therapeutic effects mediated by the EGFR/STAT3 signalling pathway on the pathogenesis of keloid scars and on normal wound healing." (PMID 29145520, 2017). "STAT3 is activated by various growth factors and contributes to keloid pathogenesis by promoting collagen production, cell proliferation, and migration." (PMID 29145520, 2017). "Lim and colleagues showed that keloid lesions fibroblasts display constitutive activation of STAT3 signalling, and blocking of this pathway inhibited the profibrotic activity of these cells." (PMID 26772733, 2016). "Stat3 is an oncogene and a latent transcription factor activated in cultured KF in vitro and thought to have an important role in keloid pathogenesis by promoting collagen expression, fibro-proliferation and cell migration." (PMID 24348987, 2013). "However, the area surrounding keloid lesions exhibits heightened expression of IL-6, which contributes to keloid formation by inducing STAT3 phosphorylation in fibroblasts." (PMID 38284901, 2024). "Research has identified STAT3 signaling as the most significantly enriched gene ontology term in keloid fibroblasts (KFs), the primary cells responsible for collagen production in keloids." (PMID 39201463, 2024). "In conclusion, DMC-HA elevates intracellular ROS levels, inhibits STAT3 phosphorylation, and activates the mitochondrial apoptosis pathway, ultimately inhibiting keloid fibroblast proliferation and promoting apoptosis, thereby suppressing keloid formation." (PMID 38284901, 2024). "This makes STAT3 a potential therapeutic target for keloids." (PMID 35628356, 2022). "Our data showed that total STAT3 was found to be increased in both keloid tissues and fibroblasts." (PMID 35628356, 2022). "It is speculated that ASC-J9, a curcumin analog that can inhibit STAT3, can inhibit the production of ROS by keloid fibroblasts." (PMID 35628356, 2022). "However, our findings were successful in uncovering that the STAT3-mediated impacts of folic acid influence the mitochondrial translocation of pSTAT3Ser727 in ways that differ between HV, keloid, and STAT3LOF fibroblast lines." (PMID 33662027, 2021). "Consistent with prior reports identifying the activity and accessibility of STAT3 as central in the hyper-proliferative/hyper-motile phenotype of keloid cells and similar to our prior findings, fibroblasts from patients with STAT3 LOF showed reduced closure in the scratch assay." (PMID 33662027, 2021). "Given that both STAT3 and JAK2 are functions are abnormal in keloid derived cells, we hypothesized that pharmacologic and mutational disruptions of JAK2/STAT3 would influence both the metabolic and proliferation/migration abnormalities seen in keloid cells." (PMID 33662027, 2021).
keloid (continued). "Decreasing the expression of STAT-3 or inhibiting its phosphorylation could significantly reduce synthesis of collagen and proliferation and migration of keloid fibroblasts, supporting a pro-fibrotic role of STAT-3." (PMID 33343575, 2020). "In particular, Stat3 confers increased cell proliferation and migration within keloid fibroblasts." (PMID 31440236, 2019). "In addition, EGCG was demonstrated to induce keloid shrinkage and inhibit growth and pathological features of keloids by suppressing STAT3 signalling." (PMID 31662773, 2019). "Interestingly, direct CP exposure did not kill either fibroblast type, but inhibited cell migration in keloid fibroblasts, associated with reduced collagen expression, suppressed ERK, Akt and STAT3 phosphorylation, while normal fibroblast migration and Akt phosphorylation was enhanced." (PMID 38785562, 2024). "However, given that folate degradation is reduced in pigmented skin and induces JAK2/STAT3, we hypothesized that greater cutaneous folate levels may contribute to keloid pathogenesis." (PMID 33662027, 2021). "Furthermore, while our findings reproduce the findings of prior reports identifying JAK1/2, STAT3, and folate as targetable pathways for the treatment of keloids, a potentially contrasting role for vitamin D impacting STAT3 signaling and risk of keloids in pigmented skin should also be considered." (PMID 33662027, 2021). "Natural products offer multifaceted therapeutic potential in keloid management by modulating fibroblast proliferation, collagen synthesis, inflammation, and key signaling pathways such as TGF-β/Smad, IL-6/STAT3, and PI3K/Akt/mTOR." (PMID 41424791, 2025). "STAT3, a protein within the STAT family, is activated through phosphorylation, a process enhanced in both keloid tissue and KFs." (PMID 39201463, 2024). "First, the Western blotting results of keloids and the adjacent normal skin from the same subjects revealed that the expression levels of STAT3, COL1A1, and FN1 were increased in keloids relative to those in normal skin." (PMID 35628356, 2022). "In healthy volunteer fibroblasts, folic acid exposure recapitulated the exaggerated closure and hyper-glycolytic state of keloid fibroblasts through JAK1/2- and STAT3-dependent pathways." (PMID 33662027, 2021). "The authors concluded that CAP can therefore have beneficial therapeutic effects on the pathogenesis of keloid scars and on normal wound healing, which are mediated by the EGFR/STAT3 signaling pathway." (PMID 34829774, 2021). "Subsequent research identified over activity of signal transducer and activator of transcription 3 (STAT3; in conjunction with JAK2) as a central mediator of keloid pathology." (PMID 33662027, 2021). "Of interest, IL-6 and its second messengers JAK/Stat3, both of which are elevated in keloid fibroblasts, form the IL-6/JAK/Stat3 pathway, which contributes toward tumorigenesis within the tumor micro-environment." (PMID 31440236, 2019). "Interestingly, both IL-6 and its second messengers, Janus kinase 2 (JAK2) and signal transducer and activator of transcription 3 (STAT3), are elevated in keloids." (PMID 39919369, 2025). "Previous studies have indicated that in vitro cultured keloid fibroblasts, similar to their normal fibroblast counterparts, either do not express phosphorylated STAT3 (p-STAT3) or express it at very low levels." (PMID 38284901, 2024). "Inhibition of EGFR/STAT3 pathway by NTP may be a useful therapeutic and preventive strategy for keloid therapy." (PMID 29145520, 2017). "Compared with normal skin and scar tissue, M2 macrophages in keloid significantly increased, and promoted the proliferation and migration of skin fibroblasts by generating connective tissue growth factor and activating ERK1/2/STAT3 and AKT/STAT3 signaling pathways." (PMID 37849830, 2023).